INS (insulin)
Diseases named in the same sentence as INS in open-access papers (continued):
Sharing a sentence is not in itself a finding about the gene and the disease.
dumping syndrome (13 papers, 2007 to 2025). A disorder of the gastrointestinal tract. "The study authors concluded that reactive hypoglycemia in dumping syndrome following bariatric surgery is caused by increased GLP-1 concentration potentiating insulin release." (PMID 35399928, 2022). "The main causes are the late dumping syndrome, factitious administration of insulin ororal hypoglycemic agents and NIPHS." (PMID 26734801, 2015). "Early dumping syndrome develops within 30 min of eating as a consequence of accelerated gastric emptying, whereas late dumping syndrome appears 1–3 h postprandially and is typically linked to excessive insulin release in response to high glucose loads in the small intestine." (PMID 41153649, 2025). "Plasma insulin concentration peaked at 60 minutes in patients with dumping syndrome, and at 90 minutes in control patients." (PMID 35399928, 2022). "Further, it is reported that dumping syndrome, one of the common complications of patients following gastrectomy, gets worse during pregnancy due to lower insulin sensitivity in a pregnant woman." (PMID 30497494, 2018). "Liraglutide is a long-acting GLP-1RA, and it inhibited insulin secretion both before and after meals in a previously reported case with late dumping syndrome, and the TIR was only 84% after the treatment of 1.2 mg liraglutide per day, which was 100% in the present case." (PMID 34032745, 2021). "In the late dumping syndrome or reactive hypoglycemia may occur neuroglycopenic symptomsin response to high insulin release by eating foods with high glycemic index." (PMID 26734801, 2015). "In this test, patients with suspected dumping syndrome ingest a mixed meal containing carbohydrates, fat and proteins after an overnight fast, and blood samples are collected prior to the meal and at 30-min intervals for up to 2 h afterwards to measure glycaemic and insulin profiles." (PMID 32457534, 2020). "The relative hypoinsulinaemia in the late phase of the test in the GBP group followed the rapid decrease in both glucose and insulin after peak concentrations in the early phase, and coincided with the time point when symptoms of the so-called dumping syndrome may occur." (PMID 17894830, 2007). "Post-prandial levels of insulin and GLP-1 normalized with nutrient administration into the stomach rather than the gastric bypass route, suggesting that altered nutrient delivery to the intestines contributes to dumping syndrome." (PMID 35399928, 2022).
glucosuria (13 papers, 2011 to 2025). "Since the known molecular mechanisms by which metformin (insulin sensitizer) and canagliflozin (causing glucosuria) exert their glucose lowering effects are completely different, a possible synergistic effect on DKD development could not be excluded." (PMID 37240387, 2023). "SGLT2i promote weight loss primarily by enhancing lipid metabolism for energy production and reducing insulin secretion; these mechanisms are driven by the glucose-deprived state resulting from glucosuria." (PMID 41303036, 2025). "The glucosuria results in lower serum glucose values which decreases insulin release and increases glucagon release from the pancreas." (PMID 31488052, 2019). "Dapagliflozin induced glucosuria (75–91 g/d), markedly lowered the fasting plasma glucose concentration, and increased insulin-stimulated whole-body glucose disposal using the euglycemic insulin clamp technique." (PMID 38426504, 2024). "Glycosuria caused by SGLT-2i decreases plasma glucose and insulin levels." (PMID 38813008, 2023). "Third, glucosuria increases both plasma glucose and insulin sensitivity." (PMID 29978156, 2017). "Because changes in plasma glucagon and insulin concentrations cannot explain the increase in EGP, we hypothesised that a renal neuronal signal is generated in response to glucosuria and leads to the stimulation of hepatic glucose production." (PMID 32827269, 2020).
hemochromatosis (13 papers, 2011 to 2024). A disorder of iron metabolism characterized by a triad of HEMOSIDEROSIS; LIVER CIRRHOSIS; and DIABETES MELLITUS. "In a murine model of hemochromatosis, iron deposition decreased insulin secretory capacity secondary to oxidative stress, and increased apoptosis in pancreatic β-cells." (PMID 38337620, 2024). "In an early study, some patients with hemochromatosis had subnormal fasting plasma insulin levels and suboptimal increments in plasma insulin levels after intravenous glucose infusions." (PMID 28331855, 2017). "The Hfe knockout mouse, the animal model of hemochromatosis, also displays alterations in pancreatic function, including decreased insulin secretory capacity." (PMID 24465846, 2014). "Patients with hemochromatosis have a higher prevalence of diabetes, decreased insulin secretory capacity, and impaired glucose tolerance relative to the normal population." (PMID 24465846, 2014). "It is unknown whether phlebotomy of all p.C282Y homozygotes will increase insulin secretion if diagnosis of hemochromatosis and induction phlebotomy therapy are early." (PMID 28331855, 2017). "In a mouse model of hemochromatosis, excess iron resulted in beta-cell oxidant stress and decreased insulin secretory capacity secondary to beta-cell apoptosis and desensitization of glucose-induced insulin secretion." (PMID 23046549, 2012). "Dolphins with hemochromatosis have higher 2 h postprandial insulin levels compared to healthy controls, and approximately 67% of MMP dolphins appear to have hemochromatosis at time of death." (PMID 24130551, 2013).
HOMA-IR (13 papers, 2014 to 2025). The HOMA-IR measurement employs the homeostatic model assessment (HOMA) to quantify insulin resistance. "An evaluation of insulin-related parameters revealed significant elevations of InS and Homa-IR in the MG compared to NC (p < 0.01)." (PMID 40647154, 2025). "The circulating levels of fasting blood, insulin, Homa-IR, blood glucose, OGTT, ITT, TG, LDL, ALT, and AST were significantly increased in the MAFLD group (p < 0.05)." (PMID 36838862, 2023). "The C-peptide, insulin secretion index, and Homa-IR in the patient were reduced after transplantation compared with those before transplantation." (PMID 36032108, 2022). "After the intervention, the levels of FBG, INS, and Homa-IR of mice in all four groups were significantly higher than those in the NC group, with statistically significant differences (P < 0.001)." (PMID 34923973, 2021). "When compared with the HF group, the levels of FBG, INS and Homa-IR of obese mice in the three intervention groups were significantly lower, with statistically significant differences (FBG P < 0.05, INS Homa-IR P < 0.001)." (PMID 34923973, 2021). "Overall, there were significant differences (p < 0.05) between the LGI and control groups with respect to weight, glycated hemoglobin, insulin, Homa-IR, triglycerides, hs-CRP and ApoB." (PMID 32867226, 2020). "We previously demonstrated an increase in Homa-IR, related to the increased insulin levels, in GHD children after GHT, and a degree of impairment of glucose metabolism during GHT has often been previously demonstrated." (PMID 28634491, 2017). "Metabolic index, heart rate, fasting sugar, insulin, Homa-IR, cortisol, cholesterol, triglyceride, high-density lipoprotein, and low-density lipoprotein between groups were similar." (PMID 25520919, 2014). "In overweight and obese controls (mean age: 25.46 ± 13.77 years, similar age than overweight and obese PKU, p = 0.72): insulin and HOMA-IR concentrations also were lower in the controls (insulin: 12.63 ± 5.87 vs 20 ± 9.39 mIU/L; p = 0.014; Homa IR 2.86 ± 1.37vs 3.95 ± 2.17, p = 0.19)." (PMID 29945661, 2018). "Substantially, our data demonstrated that all children, regardless of GHT regimen, showed a worsening in insulin sensitivity after 12 months of treatment, as demonstrated by the increase in Homa-IR, already shown in adult patients." (PMID 28634491, 2017).
lung adenocarcinoma (13 papers, 2010 to 2025). A carcinoma that arises from the lung and is characterized by the presence of malignant glandular epithelial cells. "Five hormone levels were significantly associated with lung adenocarcinoma (LUAD): luteinizing hormone, thyroid hormones, insulin, prolactin levels, and parathyroid hormone." (PMID 40017690, 2025). "Similar crosstalk between Notch and insulin signaling has been reported in lung adenocarcinoma cells under hypoxic environment." (PMID 31534459, 2019). "Immunohistochemical staining for insulin showed that lung adenocarcinoma stained positive and gastric cardia adenocarcinoma stained weakly positive." (PMID 29166433, 2019). "We conducted H3N2-based HATRIC-LRC on 20 million human lung adenocarcinoma (A549) cells and compared to the control ligand insulin." (PMID 29666374, 2018). "Fenofibrate also significantly reduced the serum insulin and insulin-like growth factor (IGF)-1 levels, and decreased the immunohistochemical expression of IGF-1 receptor (IGF-1R), phosphorylated Akt, and phosphorylated Erk1/2 in lung adenocarcinomas." (PMID 24857924, 2014).
macular edema (13 papers, 2008 to 2025). "Insulin use was significantly associated with higher DR severity (P = 0.039), while macular edema showed a strong association with advanced DR stages (P = 0.003)." (PMID 39867069, 2024). "We demonstrated an extraordinary instance of unilateral ischemia CRVO (macular edema), where the main cause of risk was insulin resistance." (PMID 39233948, 2024). "Similarly, thiazolidinediones, while improving insulin sensitivity, are associated with adverse effects, including cardiovascular risks and macular edema, limiting their broader application in AMD prevention." (PMID 39720591, 2024). "Thiazolidinediones work by reducing glucose production, increasing the sensitivity of target tissues to insulin and improving insulin resistance, but the time to clinical effect can be protracted, and these medications may also cause peripheral edema and macular edema." (PMID 24633252, 2014). "Treatment satisfaction was affected over time by the presence of DR, insulin therapy and the severity of macular edema." (PMID 25138117, 2014). "In 1995, Klein investigated reported that after a 10-year period, the incidence of macular oedema was 20.1% in the younger-onset group, 25.4% in the older-onset group receiving insulin, and 13.9% in the older-onset group not receiving insulin." (PMID 38918766, 2024).
primary immunodeficiency (13 papers, 2015 to 2025). "Hcrt expression showed significant correlations with the “ErbB signaling pathway,” “insulin signaling pathway,” “mTOR signaling pathway,” and “primary immunodeficiency,” among others." (PMID 40166636, 2025). "At level 3, compared with the G group, many pathways were enriched, such as “porphyrin and chlorophyll metabolism;” “insulin signaling pathway;” “pentose and glucuronate interconversions;” “primary immunodeficiency;” and “glycine, serine, and threonine metabolism”." (PMID 36828433, 2023). "Of interest, the effect of high fat diet induced higher expression of genes within the following classes (primary immunodeficiency, cell adhesion molecules, T cell receptor signaling, cytokine-cytokine receptor interaction, and insulin signaling), which was independent of genotype." (PMID 27330996, 2016). "In addition, cell cycle, DNA replication, insulin signaling pathway, MTOR signaling pathway, natural killer cell-mediated cytotoxicity, primary immunodeficiency, TGF beta signaling pathway, and WNT signaling pathway might be the main pathways regulated by CDC20." (PMID 35800227, 2022).
secondary hyperparathyroidism (13 papers, 2010 to 2025). Overproduction of parathyroid hormone in response to influence external to the parathyroid glands. "On the other hand, Vit D deficiency causes secondary hyperparathyroidism, which in turn inhibits calcium-related insulin secretion." (PMID 38136648, 2023). "In addition, 25(OH)D deficiency can cause secondary hyperparathyroidism (SHPT), and high parathyroid hormone (PTH) levels can inhibit insulin secretion, further aggravating IR." (PMID 34807347, 2022). "Althoughthe mechanisms involved in bone loss after RYGB remain unclear, they may involve acombination of factors including secondary hyperparathyroidism and decreased levelsof insulin and IGF1." (PMID 34878062, 2021). "The absolute lack of insulin secretion leads to PTH hypersecretion, associated with a decrease in serum Ca2+ levels and causes a secondary hyperparathyroidism." (PMID 31933638, 2019).
Shock (13 papers, 2006 to 2025). The state in which profound and widespread reduction of effective tissue perfusion leads first to reversible, and then if prolonged, to irreversible cellular injury. "An increased rate of superinfection was reported in the Corticosteroid and Intensive Insulin Therapy for Septic Shock (COIITTS) study in patients assigned to the fludrocortisone arm which we did not replicate." (PMID 39235623, 2024). "High-dose insulin (HDI) therapy has been used as inotropic support for toxin-induced cardiogenic shock, but literature suggests that it can also be used in non-toxin-induced cardiogenic shock states." (PMID 36042600, 2022).
thalassemia (13 papers, 2010 to 2025). An inherited blood disorder characterized by a decreased synthesis of one of the polypeptide chains that form hemoglobin. "Early changes in insulin sensitivity and b-cell function may help in understanding the sequences of pathophysiology underlying glucose dysregulation in thalassemia patients." (PMID 28739553, 2018). "The impaired insulin excretory function secondary to chronic iron overload in the pancreas is one of the main determinants of altered glucose metabolism in thalassemia." (PMID 41010806, 2025). "Nearly half of the children in the case group had a positive family history of thalassemia, and 68.3% of them have insulin administered once daily." (PMID 29872590, 2018). "This opinion is further reinforced by the evidence of increased fasting proinsulin levels and proinsulin-to-insulin ratio in patients with thalassemia, indicating early beta-cell damage due to siderosis." (PMID 27123460, 2016). "These preliminary results suggest that zinc status is related to glucose homeostasis and insulin secretion in patients with transfusion dependent thalassemia." (PMID 26043030, 2015). "Additionally, in thalassemia patients, insulin sensitivity can be impaired even in cases that appear normoglycemic." (PMID 40075815, 2025). "In a study on 17 normal glucose tolerance beta thalassaemia minor trait patients by Tong and colleagues (2002), fasting insulin levels were higher than control (p = 0.003) and the insulin resistance state was higher in the thalassemia trait group too (p = 0.004)." (PMID 25722965, 2015). "However, the acute effects of blood transfusion on insulin sensitivity and b-cell function in patients with thalassemia remain unknown." (PMID 28739553, 2018).
vitiligo (13 papers, 2015 to 2025). Generalized well circumscribed patches of leukoderma that are generally distributed over symmetric body locations and is due to autoimmune destruction of melanocytes. "These disruptions may produce a precarious biological milieu that disrupts insulin signaling, a fact that, in consideration of several epidemiological data, convinces us to associate vitiligo with metabolic diseases." (PMID 40277891, 2025). "Overall, for the first time, our data definitively prove insulin resistance at a cellular level in vitiligo cells." (PMID 40277891, 2025). "Collectively, in the vitiligo cells, the basal activation of mTOR, the high level of phosphorylated S6, and poor inducibility by insulin reflected in low Akt phosphorylation fully correspond to the description of cellular IR." (PMID 40277891, 2025). "Inflammatory cytokines are involved in inhibiting the insulin signaling pathway by phosphorylating serine residues of the insulin receptor substrate-1, leading to insulin resistance development in vitiligo." (PMID 36439174, 2022). "Inflammatory cytokines are involved in the inhibition of the insulin signaling pathway by phosphorylation of serine residues of insulin receptor substrate-1, which leads to the development of insulin resistance in vitiligo." (PMID 33898117, 2021). "Comparison between the vitiligo and the control groups revealed that patients with vitiligo had higher IR (2.3 versus 2.0, P < 0.01), higher insulin and C-peptide levels (P < 0.001, P < 0.001, resp)." (PMID 25977937, 2015). "Exploring this link could reveal new ways to manage vitiligo, as insulin resistance could potentially affect the inflammatory processes that contribute to skin depigmentation." (PMID 40277891, 2025). "Due to the different properties and functions exerted by FAs, an imbalance in their composition can be related to a disturbance at the level of glucose–insulin homeostasis, oxidative stress, inflammation, and mitochondrial dysfunction, all relevant features shared by both MetS and vitiligo." (PMID 39337683, 2024). "Moreover, considering that PUFAs and the correct n6/n3 ratio affect the homeostasis between glucose and insulin, their dysregulation observed in vitiligo can partly explain the tendency towards insulin resistance and altered glucose handling." (PMID 39337683, 2024). "In vitiligo cells, IGF-1 and insulin stimulation contributes to the aggravation of the energetic imbalance, a condition that promotes excessive glucose import responsible for nonenzymatic overproduction of advanced glycation end products (AGEs)." (PMID 41007740, 2025). "Overall, these studies converge in the demonstration of a higher fasting glucose level, a higher fasting insulin level, an increased total cholesterol amount, and a higher LDL/HDL ratio in the blood of vitiligo patients." (PMID 40277891, 2025). "In addition, other mechanisms may contribute to the development of MetS in patients with vitiligo, such as insulin resistance, lipid profile disturbances and other metabolic disorders, due to the increased inflammatory cytokines and autoimmune reactions of the melanocytes." (PMID 28443562, 2017). "There is also a growing understanding of the importance of insulin and IGF-1 signaling in vitiligo." (PMID 40303919, 2025). "However, IR, defined as a cellular defect in the insulin-mediated control of glucose metabolism, and its possible role in vitiligo pathogenesis has not been proven yet." (PMID 40277891, 2025). "There are no reports showing insulin autoantibodies in a case of vitiligo." (PMID 38428138, 2024).
AIDS (12 papers, 2011 to 2025). A syndrome resulting from the acquired deficiency of cellular immunity caused by the human immunodeficiency virus (HIV). "AIDS is associated with a deficiency in growth hormone, a counterregulatory hormone to insulin, although it should be noted that growth hormone excess is more typically associated with DM." (PMID 36768699, 2023). "John’s Wort which has been shown to alter drug metabolism of a number of drugs notably those used in the treatment of HIV/AIDS, warfarin, insulin, aspirin and digoxin." (PMID 29300341, 2018). "N-acetylcysteine was shown to increase whole blood glutathione levels and decrease the basal insulin reactivity in AIDS patients and non-diabetic obese patients, respectively." (PMID 36699333, 2022). "Basal insulin is usually not sufficient alone to meet insulin requirements in severely infected patients with HIV/AIDS (personal observation)." (PMID 21232158, 2011). "However, a study investigating AIDS patients who were switched to integrases found only a transient rise in glucose and no increase in insulin resistance." (PMID 36768699, 2023).
arrhythmogenic right ventricular cardiomyopathy (12 papers, 2016 to 2025). "One of the widest ranging examples among these is the p.Arg644Cys variant which has been linked to EDMD, LGMD, L-CMD, atrioventricular block (AVB), DCM, arrhythmogenic right ventricular cardiomyopathy, left ventricular noncompaction, insulin resistance, FPLD, and CMT." (PMID 36552829, 2022).